STAT4 (signal transducer and activator of transcription 4)
Description:
Transcriptional regulator mainly expressed in hematopoietic cells that plays a critical role in cellular growth, differentiation and immune response. Plays a key role in the differentiation of T-helper 1 cells and the production of interferon-gamma. Also participates in multiple neutrophil functions including chemotaxis and production of the neutrophil extracellular traps (By similarity). After IL12 binding to its receptor IL12RB2, STAT4 interacts with the intracellular domain of IL12RB2 and becomes tyrosine phosphorylated. Phosphorylated STAT4 then homodimerizes and migrates to the nucleus where it can recognize STAT target sequences present in IL12 responsive genes. Although IL12 appears to be the predominant activating signal, STAT4 can also be phosphorylated and activated in response to IFN-gamma stimulation via JAK1 and TYK2 and in response to different interleukins including IL23, IL2 and IL35. Transcription activation of IFN-gamma gene is mediated by interaction with JUN that forms a complex that efficiently interacts with the AP-1-related sequence of the IFN-gamma promoter (By similarity). In response to IFN-alpha/beta signaling, acts as a transcriptional repressor and suppresses IL5 and IL13 mRNA expression during response to T-cell receptor (TCR) activation.
Synonyms: DPMC; SLEB11
Tractability: PROTAC: ubiquitination databases record sites on it; its protein half-life has been measured; a small molecule that binds it is known.
Target class: Transcription factor
Gene: Protein-coding gene on chromosome 2 (191,029,570 to 191,178,435, reverse strand). Ensembl gene ENSG00000138378.
Subcellular location: Cytoplasm; Nucleus
Subcellular location (Human Protein Atlas): Nuclear bodies; Nucleoplasm; Flagellar centriole
Pathways (Reactome):
Immune System: Gene and protein expression by JAK-STAT signaling after Interleukin-12 stimulation; Interleukin-12 signaling; Interleukin-20 family signaling; Interleukin-21 signaling; Interleukin-23 signaling; Interleukin-35 Signalling
Developmental Biology: Differentiation of naive CD4+ T cells to T helper 1 cells (Th1 cells)
Gene Ontology:
Molecular function: DNA-binding transcription factor activity; identical protein binding; protein binding; DNA-binding transcription factor activity, RNA polymerase II-specific; RNA polymerase II cis-regulatory region sequence-specific DNA binding; DNA binding
Biological process: interleukin-12-mediated signaling pathway; response to interleukin-6; T-helper 1 cell differentiation; cell surface receptor signaling pathway via JAK-STAT; cytokine-mediated signaling pathway; defense response; positive regulation of transcription by RNA polymerase II; regulation of cell population proliferation; regulation of transcription by RNA polymerase II; response to peptide hormone; immune response; regulation of DNA-templated transcription; signal transduction
Cellular component: nuclear body; nucleoplasm; nucleus; RNA polymerase II transcription regulator complex; chromatin; cytoplasm; cytosol
Genetic constraint (gnomAD): Loss-of-function variants: 32 observed, 85.39 expected, observed/expected ratio (o/e) 0.37, 90% interval 0.28 to 0.5. The upper end of that interval is the gene's LOEUF score, 0.5, which puts it in group 2 of 6, group 1 being the genes least tolerant of losing a copy. Missense variants: 561 observed, 810.95 expected, observed/expected ratio (o/e) 0.69, 90% interval 0.64 to 0.74. Synonymous variants: 264 observed, 282.31 expected, observed/expected ratio (o/e) 0.94, 90% interval 0.85 to 1.03.
Homologues: Orthologues: chimpanzee STAT4 (100% identical), dog STAT4 (97% identical), pig STAT4 (97% identical), macaque STAT4 (97% identical), rabbit STAT4 (97% identical), guinea pig STAT4 (95% identical), mouse Stat4 (95% identical), tropical clawed frog stat4 (72% identical), zebrafish stat4 (60% identical), Caenorhabditis elegans sta-1 (21% identical), Caenorhabditis elegans sta-2 (14% identical). Paralogues in human: STAT1 (53% identical), STAT3 (48% identical), STAT2 (41% identical), STAT5B (29% identical), STAT5A (28% identical), STAT6 (24% identical).
Diseases named in the same sentence as STAT4 in open-access papers:
STAT4 is named in the same sentence as 247 diseases in open-access papers, as found by Europe PMC text mining. Sharing a sentence is not in itself a finding about the gene and the disease. The quoted sentences say what the papers report.
autoimmune disease (71 papers, 2008 to 2026). A disorder resulting from loss of function or tissue destruction of an organ or multiple organs, arising from humoral or cellular immune responses of the individual to their own tissue constituents. "Among these, STAT4 has been widely associated with increased susceptibility to various autoimmune diseases, highlighting its relevance as a genetic factor of interest in the study of these conditions." (PMID 41595492, 2026). "The transcription factor STAT4 has been implicated in the pathogenesis of autoimmune diseases, including inflammatory bowel disease, multiple sclerosis, rheumatoid arthritis, and diabetes mellitus." (PMID 40067743, 2025). "The importance of STAT4 in cytokine regulation is underscored by its association with several autoimmune diseases." (PMID 41473684, 2025). "Although various sources indicate associations of STAT4 rs10181656, rs7574865, rs7601754, and rs10168266 with inflammatory and autoimmune diseases, in our study, only rs7601754 was statistically significantly associated with the occurrence of MS." (PMID 38673659, 2024). "STAT4 plays a central role in signal transduction, particularly in facilitating the production of biomolecules closely associated with autoimmune diseases." (PMID 39575235, 2024). "The majority of STAT4 gene polymorphisms described here occur within introns, and genetic editing has confirmed that the most significantly associated SNPs linked to autoimmune disease are located in the third intron of the gene." (PMID 39575235, 2024). "Since MS is an autoimmune disease, we looked for associations between STAT4 SNPs, STAT4 serum levels, and MS." (PMID 38673659, 2024). "For example, the T allele of rs7574865 has been associated with increased STAT4 mRNA and protein levels, potentially conferring a higher risk for autoimmune disorders." (PMID 39597056, 2024). "Within the STAT4 gene, two genetic variants have been described that are involved in autoimmune diseases." (PMID 38397230, 2024). "STAT4-mediated signal transduction is known to enhance the production of autoimmune-related components implicated in the pathogenesis of autoimmune diseases such as RA, SLE, and psoriasis." (PMID 39314521, 2024). "Genetic polymorphisms in STAT4 strongly influence immune responses and disease outcomes, especially in cancer and autoimmune diseases." (PMID 39575235, 2024). "Several genetic association studies have shown evidence that mutations in the STAT4 gene are connected to an increased vulnerability to various autoimmune diseases." (PMID 38003408, 2023). "Several STAT4 single nucleotide polymorphisms (SNPs) have previously been associated with an increased risk of autoimmune diseases such as systemic lupus erythemosus (SLE), primary Sjogren’s syndrome (pSS), rheumatoid arthritis (RA) and thyroid disease." (PMID 38202017, 2023). "Studies conducted by researchers associate single nucleotide polymorphisms of the STAT4 gene rs10181656, rs7574865, rs7601754, and rs10168266 with various autoimmune diseases." (PMID 38275379, 2023). "The STAT4 rs10181656 polymorphism has been associated with autoimmune diseases such as rheumatoid arthritis, systemic sclerosis, and systemic lupus erythematosus." (PMID 38275379, 2023). "STAT4 protein is also involved in the pathogenesis of many inflammatory and autoimmune diseases and has been associated with rheumatoid arthritis and systemic lupus erythematosus." (PMID 38275379, 2023). "Signal transducer and activator of transcription-4 (STAT4) is associated with an elevated risk of various autoimmune diseases, including primary Sjögren’s syndrome, RA, and SLE." (PMID 38003572, 2023). "It is also notable that genetic variation of STAT4 has been associated with the risk of autoimmune diseases like systemic lupus erythematosus and rheumatoid arthritis." (PMID 34630419, 2021).
autoimmune disease (continued). "STAT4, the gene encoding the signal transducer and activator of transcription-4, is one of the genetic factors thought to have a role in multiple autoimmune diseases, such as rheumatoid arthritis and SLE." (PMID 33333988, 2020). "STAT4 is a risk factor for several autoimmune diseases such as rheumatoid arthritis and systemic lupus erythematosus." (PMID 33328346, 2020). "The extensive involvement of type I and type II interferons in the pathogenesis of MS and SLE made STAT4 an obvious candidate region for genetic predisposition to these autoimmune diseases." (PMID 29881250, 2018). "The scope of this study was to study the association of STAT4 (rs7582694) gene polymorphism with two autoimmune diseases, e.g., multiple sclerosis (MS) and juvenile onset systemic lupus erythematosus patients (JO-SLE) and its relation to disease severity." (PMID 29881250, 2018). "The direction of this effect suggests that, in contrast to its role in NTS-risk, increased STAT4 expression and IFNγ production enhances the risk of a range of autoimmune diseases." (PMID 29523850, 2018). "Another two Japanese studies also suggested that STAT4 is a common autoimmune diseases related genetic risk factor, including RA and SLE." (PMID 28977835, 2017). "The association between STAT4 and some autoimmune diseases, including rheumatoid arthritis (RA) or systemic lupus erythematosus (SLE) has been reported in several previous studies." (PMID 28977835, 2017). "Genetic deletion studies show STAT4 is an important factor in elevating susceptibility to several autoimmune diseases." (PMID 26555476, 2015). "The protein tyrosine phosphatase nonreceptor 22 (PTPN22) and signal transducer and activator of transcription factor 4 (STAT4) have been recognized as susceptibility genes for numerous autoimmune diseases." (PMID 25781893, 2015). "The STAT4 gene encodes a transcriptional factor that transmits signals induced by several key cytokines which play important roles in the development of autoimmune diseases." (PMID 25019342, 2014). "Of those, STAT4 particularly has been confirmed in several studies and is clearly associated with autoimmune diseases such as RA or systemic lupus erythematosus (SLE)." (PMID 23990947, 2013). "We decided to investigate for the first time the possible role of different STAT4/IL23R autoimmune disease-associated polymorphisms on the susceptibility to develop non-anterior uveitis and its main clinical phenotypes." (PMID 24312163, 2013). "This is the first study to show a positive association between a STAT4 polymorphism and type-1 autoimmune hepatitis, suggesting that autoimmune hepatitis shares a gene commonly associated with risk for other autoimmune diseases." (PMID 23990947, 2013). "A recent study showed that G allele at rs7574865 was associated with increased risk for HCC, suggesting dual roles of STAT4 in autoimmune diseases and HBV-related HCC." (PMID 23990947, 2013). "In relation to the STAT4 rs3821236 and rs7574865 polymorphisms, there was a higher heterogeneity in the reported ORs, with some autoimmune diseases showing considerably stronger signals than others (e.g. OR > 1.40 for SLE and 1.16 for RA)." (PMID 24312163, 2013). "Recent studies demonstrated an association of STAT4 polymorphisms with autoimmune diseases including systemic lupus erythematosus and rheumatoid arthritis, indicating multiple autoimmune diseases share common susceptibility genes." (PMID 23990947, 2013). "The STAT1 gene is located adjacent to STAT4 suggesting it is also a candidate susceptibility gene for autoimmune disease." (PMID 23990947, 2013). "STAT4 gene variants have also been found to be risk factors for other autoimmune diseases including rheumatoid arthritis, Crohn’s disease, asthma, systemic sclerosis, and Sjogren’s syndrome." (PMID 22729903, 2012).
autoimmune disease (continued). "Single-nucleotide polymorphisms in several transcription factors involved the type I IFN pathway (for example, IRF5, Tyk2, and STAT4) have recently been associated with a number of autoimmune diseases, including SLE and RA." (PMID 20096109, 2010). "We have also shown that the autoimmune disease associated variant of signal transducer and activator of transcription 4 (STAT4) modulates cellular sensitivity to IFN-α signaling." (PMID 20659327, 2010). "The genetic basis of autoimmune disorders like pSS exhibits pronounced population heterogeneity, and STAT4 variants may exert distinct effects across diverse ethnic cohorts." (PMID 40772275, 2025). "Given the established role of STAT4 in immune regulation and its association with other autoimmune diseases, we hypothesized that SNPs in the STAT4 gene may contribute to pSS susceptibility." (PMID 40772275, 2025). "As a result of abrogated Th1 responses, STAT4-deficient mice are resistant to the development of Th1-mediated autoimmune diseases, including EAE, RA, colitis, myocarditis, and diabetes, because they produce a smaller amount of pro-inflammatory cytokines, such as tumor necrosis factor-alpha (TNF-α)." (PMID 38673659, 2024). "Additionally, previous studies have demonstrated that the SNV rs7574865 in STAT4 is associated with several autoimmune diseases." (PMID 38397230, 2024). "A meta-analysis of the significance of STAT4 rs7574865 T1D risk allele T has confirmed its association with T1D in multiple populations, in addition to the already earlier found association with other autoimmune diseases." (PMID 35812428, 2022). "However, the association between STAT4 rs7574865 single nucleotide polymorphism and different autoimmune diseases remains controversial and ambiguous." (PMID 33585138, 2021). "The association between STAT4 and some autoimmune diseases, including rheumatoid arthritis (RA) or systemic lupus erythematosus (SLE) has been reported in several previous studies, and in a mouse model, STAT4 is considered important of Th1-dependent liver injury." (PMID 28977835, 2017). "Although several studies have reported the relationship between STAT4 and PTPN22 gene SNPs and some others autoimmune diseases, to date, less study focused on relation of STAT4 and PTPN22 gene polymorphisms and type 1 AIH risk previously, particularly for Chinese children." (PMID 28977835, 2017). "The T allele of rs7574865 in STAT4 confers risk of developing autoimmune disorders." (PMID 26569609, 2015). "However, since at least five additional SNPs in this intron have also been associated with an increased risk of developing autoimmune diseases, the region must play a relevant role in the regulation of STAT4 biology." (PMID 26569609, 2015). "Human polymorphisms link STAT4 to autoimmune disorders including T1DM." (PMID 26555476, 2015). "Since Th1 cells and Th17 cells are broadly implicated in chronic inflammatory and autoimmune diseases, STAT4 may play an important role in the pathogenesis of AITD." (PMID 25019342, 2014). "Our data suggest that STAT4 may be an “autoimmune disease susceptibility gene” and support the concept of deregulated pathways across multiple autoimmune diseases." (PMID 23990947, 2013). "STAT4 polymorphisms have been found to be associated with various autoimmune diseases." (PMID 23990947, 2013). "In addition, meta-analysis demonstrated that the STAT4 rs7574865 T allele conferred susceptibility to various autoimmune diseases, suggesting an association between STAT4 gene polymorphism and autoimmune diseases." (PMID 23990947, 2013). "Since Th1 and Th17 cells have the capacity to cause autoimmunity, STAT4 may play a crucial role in the development of autoimmune diseases, including AIH." (PMID 23990947, 2013). "In addition to their influence on autoimmune disease susceptibility, STAT4 polymorphisms can also influence disease phenotypes." (PMID 23990947, 2013).
autoimmune disease (continued). "To determine whether the observed association of the STAT4 gene SNPs with disease susceptibility was caused by other autoimmune diseases associated with AIH, we stratified type-1 AIH patients without other overlapping autoimmune diseases." (PMID 23990947, 2013). "Notably, STAT4 is the protein of STAT protein family, and closely related to the development of some tumors and autoimmune diseases, activated STAT4 is overexpressed in epithelial cells of ovarian cancer, and STAT4 overexpression is associated with adverse outcomes of ovarian cancer patients." (PMID 38737443, 2024). "This evidence proposes that STAT4 may function as a common risk factor in various autoimmune diseases, indicating that the block associated with BD might be distinct from the block associated with other autoimmune diseases such as RA and SLE." (PMID 38397230, 2024). "Interestingly STAT4 polymorphisms have been associated with other major autoimmune diseases." (PMID 31803181, 2019). "We hypothesized that STAT4 (rs7582694) gene polymorphism contribute to autoimmune diseases." (PMID 29881250, 2018). "In line with previous reports of significant associations of genetic variants in the STAT4 gene with the risk for autoimmune diseases such as SLE, rheumatoid arthritis and psoriasis, our study could identify the STAT4 SNP rs7574865 also to be associated with the susceptibility to CD." (PMID 20454450, 2010). "In the autoimmune diseases RA and SLE, STAT4 and STAT5 have been implicated in sex‐biased disease pathogenesis, as these STATs are expressed at higher levels in females." (PMID 41574968, 2026). "In autoimmune diseases such as multiple sclerosis (MS) and rheumatoid arthritis (RA), both STAT4 and OPN contribute to Th17 cell expansion and IL-17 production, exacerbating inflammation." (PMID 41222876, 2025). "SNPS in genes: PADI4 (rs2240340), STAT4 (rs7574865), CD40 (rs4810485), PTPN22 (rs2476601), and TRAF1 (rs3761847) have been described as risk factors for the development of autoimmune diseases, including RA." (PMID 37108746, 2023). "Junfeng Zheng and co-authors conducted a systematic review study, in 2013, which showed that the STAT4 rs7574865 SNP is associated with three autoimmune diseases, RA, SS, and SLE, and that the STAT4 rs7574865 T allele increases the probability of disease." (PMID 38275379, 2023). "Studies have reported increased STAT4 mRNA and protein expression in patients with an autoimmune disorder, including SLE." (PMID 36980810, 2023). "Consistent with its role in the immune response, STAT4 has been shown to be involved in the pathogenesis of autoimmune diseases including inflammatory bowel disease, multiple sclerosis, rheumatoid arthritis and diabetes mellitus." (PMID 36548135, 2022). "Recently, the STAT4 gene's influence on autoimmune disease has been widely studying in many different immune-related diseases." (PMID 33585138, 2021). "Numerous genome-wide association studies (GWAS) on SLE patients have identified variants in the STAT4 gene that are associated with an increased risk of developing SLE and other autoimmune diseases." (PMID 33446493, 2021). "Reassuringly, many recapitulated genes are well-established for the traits, such as CACNA1C for schizophrenia, TCF7L2 for T2D, APOB for lipids, and STAT4 for autoimmune diseases." (PMID 33990562, 2021). "In this review, we discuss the cytokines activating STAT4 in different cells, as well as the role of STAT4 in inflammation and complex diseases, especially autoimmune diseases." (PMID 32226303, 2020). "This is in line with our previous studies showing the upregulation of T-bet and the activity of the IL-12/STAT4 axis in memory T cells isolated from inflamed tissues of patients with autoimmune diseases including RA." (PMID 30574141, 2018).